GPD2 (glycerol-3-phosphate dehydrogenase 2)
Diseases named in the same sentence as GPD2 in open-access papers (continued):
Sharing a sentence is not in itself a finding about the gene and the disease.
tumor (23 papers, 2013 to 2025). "Glycolysis is accomplished through a series of enzymatic reactions in the cytoplasm, and the increased expression and activity of its associated enzymes are essential in tumor cells, among which GPD2, GPI, Hsp90α and PGK2 are involved in promoting glycolysis and cancer cell proliferation." (PMID 39509399, 2024). "Supporting this is that the roles of each GPD are mostly opposite in cancer, with GPD1 generally acting as a tumor suppressor and GPD2 acting as a tumor promoter." (PMID 38689091, 2024). "In fact, IL‐1β promotes glycolysis in gliomas through the IL‐1β‐protein kinase‐δ (PKCδ)‐glycolysis enzyme‐3‐phosphate dehydrogenase (GPD2) axis, which reprograms cellular metabolism and can promote tumour proliferation and tumour metastasis." (PMID 38652105, 2024). "Glycerol-3-phosphate dehydrogenase 2 (GPD2) is a widely existing protein pattern sequence in biology and is closely related to tumor progression." (PMID 39054490, 2024). "Overall, GPD2 seems to have generally tumor-promoting effects, with higher expression in tumor tissues." (PMID 38689091, 2024). "In general, most studies have shown that high expression of GPD2 promotes tumor progression, and inhibiting GPD2 expression has potential therapeutic effect, which is consistent with our findings." (PMID 39054490, 2024). "Further mechanistic investigation revealed the role of the GPD2-DHAP-ether lipid-AKT axis in tumor cell growth." (PMID 38689091, 2024). "For natural products, scopolin, esculetin, and taraxasterol inhibited tumor growth by suppressing GPD2-related glycolysis." (PMID 38689091, 2024). "Highlighting the anti-correlation of GPD1 and GPD2 in cancer, a recent study showed that GPD1 has tumor-promoting effects and that GPD2 has tumor-suppressing effects." (PMID 38689091, 2024). "For the next set of experiments, we conducted RNA-Seq using 4T1 and 4T1 GPD2 KO cells in an attempt to uncover the factors by which GPD2 affects tumor progression unrelatedly to bioenergetics." (PMID 36632231, 2023). "We confirmed that HIF1α can negatively regulate the expression of GPD2 at the transcriptional level, thereby inhibiting tumor progression, which is new mechanism-of-action for HIF1α as a tumor suppressor." (PMID 34098990, 2021). "Based on metabolic modeling analysis, we identified four target genes, namely SOAT1, CRLS1, ACACB, and GPD2, whose inhibition can block the growth of ccRCC tumor cells with relatively low toxicity to normal tissue cells." (PMID 34258555, 2021). "Additionally, the high expression of GPD2 (mitochondrial glycerol-3-phosphate dehydrogenase 2) in CCA is closely related to tumor cell proliferation and migration." (PMID 41394868, 2025). "Nevertheless, as in the GPD1 case, there can be some specific contexts where GPD2 may have tumor-suppressive roles, and the extent of these effects should be addressed in future studies." (PMID 38689091, 2024). "The effect of GPD2 on drug sensitivity and tumor grade/prognosis was also investigated." (PMID 38689091, 2024). "The effects and therapy values of GPD2 in tumor progression have been explored." (PMID 39054490, 2024). "Notably, when all the cancer types were combined, the expression levels were higher in tumor tissues, and higher GPD2 levels were correlated with poorer survival." (PMID 38689091, 2024). "This study suggests that isoscopoletin may exist an anti-tumor effect by regulating the glycolysis-related proteins GPD2, GPI, Hsp90α and PGK2, inhibiting the glycolysis process in HCC cells, then blocking the energy supply of tumor cells." (PMID 39509399, 2024). "Combined with proteomics, in vitro and in vivo experiments, these results demonstrate that esculetin could play an anti-tumor role by inhibiting the activity of glycolysis-related enzymes, among which GPD2 and GPI have a strong binding." (PMID 32292350, 2020).
tumor (continued). "The KEGG signaling pathway enrichment results also indicated that isoscopoletin might play an anti-tumor role by affecting the core targets of glycolysis pathway, such as GPD2, GPI, Hsp90AA1 and PGK2, which were the intersection of most glycolysis-related pathways." (PMID 39509399, 2024). "Additionally, it would be interesting to determine whether patients with high GPD1 and/or GPD2 levels in their tumor tissues might respond better to metformin treatment." (PMID 38689091, 2024). "In this study, by applying metabolomics, transcriptomics, and biochemical approaches using mtDNA-deficient, ρ0, and GPD2 KO cells, we uncovered a novel, non-bioenergetic role of mitochondrial GPD2 that is linked to ether lipids' cancer-cell-growth and tumor-progression-related functions." (PMID 36632231, 2023). "Knockdown of GPD2 can inhibit CCA cell proliferation and enhance CD8+ T-cell anti-tumor immune responses." (PMID 41394868, 2025). "Among them, GPD2, GPI, HSP90AA1 and PGK2 are involved in promoting glycolysis and tumor cell proliferation." (PMID 39509399, 2024). "In summary, our results suggest that isoscopoletin plays an anti-cancer role by regulating glycolysis-related proteins GPD2, GPI, Hsp90α and PGK2, and then inhibiting the glycolysis process and proliferation of tumor cells." (PMID 39509399, 2024). "Measurement of the target protein in tumor tissue showed an increase in PGK2, GPD2 and GPI in response to esculetin treatment." (PMID 37175299, 2023). "Target protein measurement of the tumor tissue revealed an increase in PGK2, GPD2, and GPI in response to the esculetin treatment." (PMID 32292350, 2020). "Many experiments show that the PGK2, GPD2), and GPI are key enzymes of glycolysis, and in promoting tumor cells play an important role in the process of glycolysis." (PMID 32292350, 2020). "Notably, the tumor-suppressing effects of GPD2 and mitochondrial GPX4 against ferroptosis are additive, highlighting the contribution of GPD2 in mitochondrial ferroptosis resistance." (PMID 37548939, 2024). "The largest number of changes in gene expression (n = 8) between tumour and non-malignant groups were identified in metabolic genes (PFKL, ATP5A1, UQCRFS1, CPT2, COX5A, ACLY, GPD2, and G6PD)." (PMID 36142793, 2022).
cancer (19 papers, 2014 to 2025). A tumor composed of atypical neoplastic, often pleomorphic cells that invade other tissues. "Gpd2 is closely associated with macrophage-mediated inflammatory responses and glycolysis in cancer cells." (PMID 41007695, 2025). "To determine whether mitochondrial GPD2 has a causative role in cancer cell proliferation, we followed pharmacological and genetic approaches." (PMID 36632231, 2023). "Therefore, the role of GPD2 may be implicated over a wider range of human cancers, making the enzyme a promising target for cancer therapy." (PMID 36632231, 2023). "There are still apparent discrepancies in the role of GPD2 in cancer, and therefore, it is crucial to study the detailed mechanism by which GPD2 regulates cancer growth." (PMID 38689091, 2024). "For example, a study focusing on metabolism under CI-compromised conditions showed that GPD2 was responsible for the majority of CI-independent OCRs in cancer cell lines that generally have high CI-independent OCRs, such as OVCAR438." (PMID 38689091, 2024). "The study reported that knockdown the expression of GPD2 in liver cancer cells can disrupt the homeostasis of energy metabolism and decrease cancer development and progression." (PMID 39054490, 2024). "Subsequent investigations demonstrated that supplementing cancer cells with G3P attenuates ferroptosis induced by GPX4 inhibitors in a GPD2-dependent manner." (PMID 38540171, 2024). "Compared to other components of the bioenergetic machinery, e.g., the TCA cycle, glycolysis, and the ETC, much less is known about the roles of GPS or its components GPD1 and GPD2 in cancer." (PMID 38689091, 2024). "Despite evidence of GPD2-driven ROS generation in different tissues and its roles in tissue functions, its contribution to cancer still requires more evidence in terms of the involvement of different ROS forms and regulators of GPD2-driven ROS generation." (PMID 38689091, 2024). "A broader investigation of the expression of GPD2 revealed that its level is higher in tumors than in normal tissues in most cancer types and that higher GPD2 expression is correlated with poorer survival in some cancers." (PMID 38689091, 2024). "The deletion of GPD2 in cancer cells heightens their sensitivity to mitochondrial lipid peroxidation and ferroptosis caused by GPX4 inhibition." (PMID 38540171, 2024). "In cancer, GPD2-driven bioenergetic mechanisms involving glucose have also been described in several cancer types." (PMID 38689091, 2024). "To date, numerous studies have explored the involvement and mechanisms of GPD1 and GPD2 in cancer and other diseases, encompassing reports of controversial and non-conventional mechanisms." (PMID 38689091, 2024). "Our study revealed that the DHAP/G3P ratio regulated by GPD2 affects plasmalogen lipid synthesis that, in turn, regulates important signaling pathways in cancer." (PMID 36632231, 2023). "Further investigation revealed that cancer cells supplemented with G3P attenuated ferroptosis induced by GPX4 inhibitors in a GPD2-dependent manner." (PMID 38155662, 2023). "In conclusion, our data suggest a new GPD2-ether lipid-Akt axis, whereby mitochondrial GPD2 regulates cancer cell growth by regulating plasmalogen level with ensuing activation of the Akt pathway." (PMID 36632231, 2023). "Deletion of GPD2 in cancer cells increased their sensitivity to mitochondrial lipid peroxidation and ferroptosis caused by GPX4 inhibition." (PMID 38155662, 2023). "Taken together, the previous relevant results and our present results argue against GPD2's major roles in regulating mitochondrial bioenergetics or ROS in the context of cancer cell growth." (PMID 36632231, 2023). "On the other hand, increased cell growth by supplementation of either DHAP precursor or plasmalogen in GPD2 KO cells points to ether lipid biosynthesis as the primary role of GPD2 in cancer cell growth." (PMID 36632231, 2023).
cancer (continued). "Having uncovered a plausible mechanism by which GPD2 regulates cancer, we next explored the relevance of the enzyme in different types of human cancer." (PMID 36632231, 2023). "The results presented here demonstrate that inhibitors of mitochondrial GPD2 activity elicit anti-proliferative effects on cancer cells." (PMID 24521925, 2014). "Intriguingly, the expression of GPD2 (and also AIFM2, which encodes FSP1) showed a mutually exclusive expression pattern, whereas DHODH showed a positive correlation with LDHB in a large collection of cancer cell lines." (PMID 40090955, 2025). "Although the ROS or bioenergetic mechanism of GPD2 in cancer growth is related to well-established functions of GPD2 in normal physiology, recent reports have studied less-explored aspects of GPD2-mediated metabolism for cancer growth or survival: ether lipids or lipid peroxidation." (PMID 38689091, 2024). "Additionally, this DHAP-related mechanism seems to be the first by which GPD2 modulates one of the most altered signaling pathways in cancer, the PI3K/AKT/mTOR pathway." (PMID 38689091, 2024). "Studies show that two types of GPDs, GPD1 and GPD2, can affect cancer growth differently." (PMID 38689091, 2024). "As a well-recognized function, GPD2 transfers reducing equivalents to the ETC, specifically to complex III (CIII), it may be worth discussing the bioenergetic contributions of GPD2 in both cancer and non-cancer contexts." (PMID 38689091, 2024). "GPD1 usually stops cancer cell growth, while GPD2 often encourages it." (PMID 38689091, 2024). "GPD2 was observed to be excessively active in numerous cancers." (PMID 36677837, 2023). "Therefore, the examples of DHODH and GPD2 demonstrate the importance of mitochondria-driven biosynthesis in cancer biology along with mitochondria's established bioenergetic, epigenetic, and catabolic roles." (PMID 36632231, 2023). "However, the ether lipid level in cancers was found to be elevated relative to normal tissues 43, 45, 46, which is consistent with the higher level and activity of GPD2 in many types of cancer." (PMID 36632231, 2023). "There also have been several studies indicating the contribution of GPD2 to cancer." (PMID 36632231, 2023). "In this respect, an important finding by us is that GPD2-mediated ether lipid biosynthesis activates the Akt signaling pathway, which suggests that ether lipids present a mechanistic link between GPD2 and the Akt pathway in cancer cells." (PMID 36632231, 2023). "As GPD2 elevation was also demonstrated in many fast-growing tumors 70, 71, GPD2 may be a new mitochondrial target for cancer cell metabolism." (PMID 36632231, 2023). "Notwithstanding the notion that further studies are needed to unravel the details of this hypothesis, our study provides a novel role for GPD2 in cancer unrelated to its involvement in bioenergetics, pointing to its key role in anabolic processes." (PMID 36632231, 2023). "To directly verify the hypothesis that lower level of DHAP, and its product plasmalogens, is responsible for the slower growth of cancer cells, we supplemented GPD2 KO cells with plasmalogen PC (18:0p/18:1), which was lower in the KO." (PMID 36632231, 2023). "Thus, our understanding of the role of GPD2 in cancer growth is mostly related to its 'conventional' bioenergetic functions in glycolysis and OXPHOS." (PMID 36632231, 2023). "Metformin, a GPD2 inhibitor, leads to an increase in the concentration of G3P in cancer cells." (PMID 35836291, 2022). "Consequently, we initiated an approach for the development of GPD2 inhibitors as potential cancer therapeutic agents." (PMID 24521925, 2014). "Overall, several mechanisms may influence the role of GPD2 in cancer cell growth." (PMID 38689091, 2024). "Pathways in cancer, central carbon metabolism in cancer, glycolysis/gluconeogenesis, and so on also suggested that isoscopoletin might affect the expression and activity of cancer-related proteins by binding to GPD2, GPI, Hsp90AA1 and PGK2." (PMID 39509399, 2024).
cancer (continued). "Therefore, our present results can be considered to extend the ether lipid-Akt link to non-neuronal, cancer cells and to associate it with GPD2." (PMID 36632231, 2023). "Moreover, a study in Canada suggested that GPD2 can be a target for cancer therapeutics." (PMID 31815134, 2019). "In addition to their potential usage as anti-cancer drugs, the small molecules identified here could be developed into valuable tools for analyzing the catalytic mechanisms of GPD2 and probing its ROS-generating mechanism at the molecular level." (PMID 24521925, 2014). "When esculetin exhibits an anti-cancer effect, GPI, GPD2, and PGK2 with a higher degree were selected for the following experiments." (PMID 32292350, 2020). "Importantly, it was not GPD2-mediated bioenergetics, e.g., respiration or ATP generation, but GPD2-derived DHAP and the resulting ether lipid biosynthesis that were critical for the cancer growth." (PMID 38689091, 2024). "In this review, we combined several critical studies on the roles of the GPS proteins GPD1 and GPD2 to summarize the current understanding of the metabolic and functional impacts of GPS, particularly focusing on their involvement in diseases such as cancer." (PMID 38689091, 2024). "Then, the anti-cancer effect may contain attenuating the conformational changes required for PGK2, GPD2, and GPI activation." (PMID 32292350, 2020). "The drug may treat cancer by binding to PGK2, GPD2, and GPI and inhibit their energy metabolism and activity." (PMID 32292350, 2020). "Data analyses based on multiple bioinformatics tools produced a large body of biologically meaningful information, and revealed a number of genes such as SAMHD1, G6PD, GPD2 and ENO1, which have been reported to be related to immune response, blood biology, bone remodeling, and cancer respectively." (PMID 27878450, 2017). "The roles of GPD2 in cancer cell growth, however, have not been well defined." (PMID 36632231, 2023).
infection (3 papers, 2015 to 2025). The state of being infected such as from the introduction of a foreign agent such as serum, vaccine, antigenic substance or organism. "For the direction of AM polarization, glycerol-3-phosphate dehydrogenase 2 (GPD2) was found to shift the metabolic pattern of M1 macrophages during infection and promote the activation of the M2 phenotype during tissue repair by modulating glycolysis." (PMID 41383596, 2025). "Early down-regulated genes included the glycerol biosynthetic genes GPD2 and RHR2, a likely reflection of metabolic feedback from high levels of the kidney osmoprotectant glycero-phosphocholine, which is utilized by C. albicans during infection." (PMID 25693184, 2015).
GPD2 also shares sentences with these, for which no sentence is quoted: hepatocellular carcinoma (3 papers); melanoma (3); breast carcinoma (2); Insulin resistance (2); astrocytoma (1); brain disease (1); cardia cancer (1); cardiovascular disease (1); colon cancer (1); diabetic retinopathy (1); Duchenne muscular dystrophy (1); endometriosis (1); Hyperinsulinemia (1); Infertility (1); intrahepatic cholangiocarcinoma (1); ischemic disease (1); kidney cancer (1); kidney disease (1); lactic acidosis (1); liver steatosis (1); medulloblastoma (1); metastatic melanoma (1); metastatic tumors (1); myocardial infarction (1); Obesity (1); papillary thyroid cancer (1); rotator cuff tears (1); skin melanoma (1); steatosis (1); Still's disease (1).